TNF (tumor necrosis factor)
Diseases named in the same sentence as TNF in open-access papers (continued):
Sharing a sentence is not in itself a finding about the gene and the disease.
tumor (continued). "TNF-α can promote tumor-cell apoptosis, while TGF-β1 plays a role in suppressing immune responses in the tumor microenvironment." (PMID 38257247, 2024). "The levels of proinflammatory cytokines IFN-γ and TNF-α, exhibited elevation, while the anti-inflammatory factor TGF-β demonstrated a modest decrease upon the scrutiny of cytokine levels in both the tumor and serum." (PMID 38352877, 2024). "On the contrary, the expression of TNF-α and IFN-γ in tumor tissues was lower than normal tissues and paracarcinoma tissues (P < 0.05)." (PMID 36865498, 2023). "As proof, lncRNA GAS5 can also enhance the tumor elimination ability of NK target gastric cancer by promoting the secretion of IFN-γ and TNF-α via regulating miR-18a." (PMID 37637063, 2023). "Mechanistically, TH-302 NPs reduced the expression of HIF-1α and PD-L1, facilitated the infiltration of CD8+ T cells and increased the levels of TNF-α, IFN-γ, and granzyme B in tumours, thereby enhancing the efficacy of α-PD-1 therapy." (PMID 37993847, 2023). "Among the eight tumor-related genes, ABCA1 and PLA2G7 were found to be significantly related to TNF." (PMID 36843944, 2023). "Last, NvIH enhanced the fraction of circulating CD4+ and CD8+ T cells and cytokine-secreting (IFN-γ, TNF-α) CD4+ and CD8+ T cells, which contributed to the protective immunity against tumor rechallenge." (PMID 37450588, 2023). "The pathways that were downregulated after therapy, including TNFα or TGF-beta, are consistent with response to radiation and chemotherapy representing protein release from dying cells and residual/proliferating tumor cells." (PMID 37637066, 2023). "After therapy, there was a considerable rise in immune cytokines TNF-α, IL-6, and IFN-γ in peripheral blood serum, as well as a robust infiltration of CD8+ T cells at primary and distant tumor sites, resulting in systemic therapeutic antitumor effects." (PMID 36987269, 2023). "Our computational model revealed a potential role for tumor-derived TNF-α in the delayed migration of LCs, which was experimentally validated by measurements of TNF-α expression of in vivo tumors." (PMID 37043573, 2023). "High expression of TNF-α, IL-1β, NOS2 and CD86 implied the polarisation of HF-CAR-PMs inside HER2+ tumours toward M1 phenotype." (PMID 37386139, 2023). "focused on stimulating neutrophils with TNF‐α and anti‐CD40 antibody and examining anti‐tumor killing by ADCC via tumor‐binding antibodies." (PMID 38062888, 2023). "Another STING agonist, SHR1032, is tumor protective in murine CRC by stimulating the type 1 IFNs, TNF-α, and IL-6 release in the TME." (PMID 37380989, 2023). "Macrophages in the tumor microenvironment regulate inflammation and adaptive immunity by producing growth factors (e.g., TGF-β1) and cytokines (e.g., TNF-α and IL-6), thereby enhancing angiogenesis." (PMID 36874003, 2023). "In comparison to the free drug combination, the nanoconjugate significantly reduced tumor volume, prolonged survival rate, and remarkably suppressed expression levels of NF-κB p65, COX-2, TNF-α, and Ki-67 in mice bearing an Ehrlich Ascites Tumor (EAT)." (PMID 37242604, 2023). "We treated the CT26 tumor cell line with inflammatory cytokines IFN-γ and TNF-α for 24 hours and observed a 1.3-1.5-fold increase in the MFI of CX3CR1 expression compared with untreated cells." (PMID 37771579, 2023). "CD30 is a transmembrane protein (TNFRSF8) that belongs in the Tumor Necrosis Factor (TNF) family and is abnormally expressed in tumor cells." (PMID 38251321, 2023). "Tumor cells activated by BCG can induce NETs through their production of IL-8 and TNFα, and these NETs help to recruit T cells and macrophages and repair damaged tissue, inducing tumor cell apoptosis and cell cycle arrest." (PMID 37188184, 2023). "Cytotoxic CD8+ T lymphocytes not only directly kill tumor cells through perforin and granzyme pathways or the Fas/Fas ligand (FasL) pathway but also indirectly eliminate tumor cells by secreting cytokines such as IFN-γ and TNF-α." (PMID 37836576, 2023).
tumor (continued). "In line with this study, it was reported that activated inflammatory DCs induced γδT17 cells to secrete CXCL8, TNF-α and CSF2 with a concomitant accumulation of PMN-MDSC with high arginase-1 and ROS production in the tumor." (PMID 37566060, 2023). "The treatment of leukemia mice with Tie2-monocytes, engineered for the release of IFNγ and TNFα, induced the activation of the CD8 + effector T cells, but also of MHC II + memory T cells and significantly delayed tumor progression." (PMID 36854896, 2023). "CD4 + memory T cells can release some anti-tumor molecules such as IFN-γ, TNF-α, and Granzyme B. Therefore, a high frequency of these cells in the TME is associated with better survival of patients with cancer." (PMID 37221555, 2023). "TAMs have M1 macrophage characteristics, and M1 TAMs exhibit high amounts of pro-inflammatory factors (e.g. TNF-α) and anti-tumour factors IL-12, IL-13, IL-1, and TNF-β, which can boost Th1 responses and tumour-killing capability." (PMID 37304305, 2023). "Tumor-infiltrating TH1 cells secrete IFN-γ and TNF-α, which activate macrophages toward the pro-inflammatory M1 phenotype." (PMID 37371612, 2023). "Tumor-derived EVs that contain miR-203 can inhibit DC maturation via the downregulation of the expression of TLR-4 and Tumor Necrosis Factor alpha (TNF-α), impairing the capacity to mediate IL-12-dependent Th1 differentiation." (PMID 37175226, 2023). "In mice, PDT with the particles on tumors induced DC maturation in the tumor-draining lymph nodes and elevated blood levels of IL-12p40, IFN-y, and TNF-a 3 days after treatment." (PMID 36839652, 2023). "TNF-α and IL1-β are pro-inflammatory cytokines that increase macrophages’ cytotoxicity against tumor cells." (PMID 36903405, 2023). "SPP reduced TNF-α and IL-2 levels while increasing INF-γ levels in the serum of tumor-bearing nude mice." (PMID 37538184, 2023). "TNF-α-induced NF-κB activation regulates the expression of multiple inflammation factors, which leads to a cytokine milieu in the TME that is required for tumor progression." (PMID 38201482, 2023). "Tumor necrosis factor (TNF)-related apoptosis-inducing ligand (TRAIL) plays an important role in apoptosis and tumor immunosurveillance." (PMID 37345089, 2023). "In the inhibitory tumor microenvironment, T cells show an “exhausted” phenotype; production of IFN-γ and TNF-α was shown to maintain cytotoxic T cell stimulation and increase the cytotoxic effects of CD8+ T and NK cells." (PMID 37205112, 2023). "Tumor-derived EVs inhibit NK cell cytotoxicity by decreasing the expression of NKG2D, INF-γ and TNF-α." (PMID 37064113, 2023). "In tumor-dLN, there was an increased frequency of resident CD4+ T cells and enhanced IFNγ and IFNγ+ TNF producing CD8+ and CD4+ T cells in mice with macrophage-specific PP2AcKO." (PMID 36757811, 2023). "TNF stimulates T-cell extravasation on tumor vessels and IL6 trans-signaling enhances T-cell transmigration on tumor vessels." (PMID 37069585, 2023). "Tumor necrosis factor alpha (TNF-α) is a cytokine that plays a critical role in regulating inflammation, immunity, cellular homeostasis, and tumor progression." (PMID 37711747, 2023). "The biNV-IL-15 treatment induced much higher TNF-α and IFN-γ secretion than IL-15+biNV in 4T1 and CT26 tumor models." (PMID 37875481, 2023). "The expression levels of TNF-α, IL-6, and IL12p70 were upregulated in vivo and in vitro, and the infiltration of immune CD4 and CD8 T cells was detected in tumor tissues under laser irradiation." (PMID 37896250, 2023). "Radiotherapy can also induce the expression of various proinflammatory cytokines, such as interleukin-1β (IL-1β) and tumor necrosis factor α (TNF α), which can induce the tumor’s inflammatory microenvironment and increase its immune tumor necrosis factor." (PMID 36761954, 2023).
tumor (continued). "In concert with tumor-produced LIF that expands the quantity of splenic HSPC niche cells, tumor-derived IL-1α induces TNFα expression by HSPCs to alter niche function into favoring increased EMH." (PMID 37134077, 2023). "Although nanobody-based CAR-T cells and 376.96 scFv-based CAR-T cells have comparable cytotoxicity against IMR5 tumor cells, a significantly higher level of cytokines (IFN-γ, IL-2, and TNF-α) was released from B12(VHH)-CAR-T cells compared to others." (PMID 37739951, 2023). "Increases in pro-inflammatory (TNFα, IL-6, and MHC-II) and decreases in pro-tumor (VEGF, CCL2, and CD206) markers in WT tumor-educated BMDMs treated with 100 nM CDDO-Me suggest beneficial polarization of macrophages in vitro." (PMID 36670978, 2023). "Consistent with previous reports in murine tumors, high NOS2 expression requires IFNγ and TNFα/IL1, which exhibit a striking difference in cytokines produced during induction of murine macrophages and tumor cells." (PMID 37169743, 2023). "The micelle formulation inhibited tumor growth in the C57BL/6 mouse model by inducing robust anti-tumor immune responses, such as higher levels of TNF-α, IL-12, and IL-6 than the control group." (PMID 36986636, 2023). "In the presence of inflammatory cytokines such as interferon-gamma (IFN-γ) and tumor necrosis factor-alpha (TNFα), the BBB vasculature at the local tumor site becomes “activated”, leading to upregulation of PDL1/2 ligands that increase T cell exhaustion." (PMID 37345193, 2023). "TNFα, a member of the TNF superfamily, is a pro-inflammatory cytokine, initially identified as an inducer of cell death in tumor cells." (PMID 36902036, 2023). "Heteroctenus junceus scorpion venom, depending on the concentration and incubation time, promotes a decrease in the cytokines IL-6, IL-1β and IFN-γ; as well as an increase in TNF-α and IL-12 in the supernatant of the F3II tumor cells." (PMID 38137888, 2023). "Fittingly, in our study, TNFα was a strong stimulator of vault RNA, MVP, and TEP1 gene expression and also MVP protein expression in the TNFα-responsive BON tumor model." (PMID 36980669, 2023). "Our results showed that pro-inflammatory and tumor-promoting factors MMP9, IL-8, OSM, IL-1β, TNF-α, CXCL3, and ROS all increased to varying degrees after OCOs stimulation." (PMID 37644468, 2023). "We found that tumor-specific CD8+ TILs produced more IFNγ; blood-derived tumor-specific CD8+ T cells produced more TNF and IL-2 after restimulation with PMA and ionomycin and contained more poly-functional (IFNγ/TNF/IL-2-coexpressing) cells." (PMID 37045833, 2023). "The infiltration of CTL into the tumor was significantly increased after PTI treatment, which was 1.8-fold higher than that in the oxaliplatin group, and the secretion of IFN-γ and TNF-α was promoted." (PMID 37766117, 2023). "Thus, anti-tumor immune response and prevention of neoplastic progression are mediated by cytokine control with anti-inflammatory therapy to reduce over-stimulated pro-inflammatory response, displayed by eicosanoids and cytokines, including TNF-α, and IL-644–46." (PMID 37507468, 2023). "Higher levels of pro-inflammatory TNF-α and IL-1RA were also identified in ACM derived from OGJ patients with early-stage tumours compared with late-stage tumours." (PMID 36790524, 2023). "EMT in cancer is largely driven by tumor hypoxia and resultant HIF-1α activation, as well as by inflammatory cytokines IL-6, IL-8, IL-15, and tumor necrosis factor-α (TNF-α)." (PMID 38239394, 2023). "CD8 T-cells can kill tumor cells through various mechanisms, including the secretion of IFN-γ and TNF-α and the expression of death receptor ligands such as the Fas ligand (FasL)." (PMID 37174089, 2023). "Tumor necrosis factor-α (TNF-α), granulocyte colony-stimulating factor, interleukin-1 (IL-1), and IL-6 are produced by tumor cells and can induce a tumor-related systemic inflammatory reaction (SIR)." (PMID 36719281, 2023).
tumor (continued). "These are known to be upregulated on tumour cells in response to pro-inflammatory cytokines such as interferon γ (IFN-γ) and tumour necrosis factor α (TNF-α), while co-stimulatory molecules including CD80 and CD86 are downregulated." (PMID 37835491, 2023). "Rosuvastatin was reported to inhibit pro-inflammatory cytokines including tumor necrosis factor-α (TNF-α), IL6, and TGF-β in mice, leading to tumor shrinkage." (PMID 36986550, 2023). "Levels of Inflammatory cytokines such as IL-6, MCP-1, and TNF-α were altered in serum, but increased TNF-α and NOS in tumor tissues was observed, even more so when augmented with nitroglycerin." (PMID 37514190, 2023). "Both TNF-α and IFN-γ in serum and tumor increased after 6 h of GSDMBNT mRNA@LNP treatment and maintained elevated levels for 3 days." (PMID 37454146, 2023). "Once activated, tumor-infiltrating MAIT cells display decreased IFN-γ and TNF-α and increase IL-17 production." (PMID 37529610, 2023). "Therefore, suppressing the activity of TNFα may exert an anti-tumor effect." (PMID 36996146, 2023). "These are killing tumor cells and secreting inflammatory cytokines, such as IFN-ɣ, TNF, and GM-CSF, to promote anti-tumor activity." (PMID 36721212, 2023). "Mechanistic studies revealed that PAR1CAR-T cells produced cytokines (e.g., tumor necrosis factor (TNF)-α and interferon (IFN)-γ) upon stimulation with PAR1+ tumor cells and acquired potent cytolytic activity against PAR1+ tumor cells." (PMID 37667257, 2023). "MiR-4669-enriched exosomes suppressed CD80 and TNF-α in RAW264.7 cells, suggesting a direct impact of exosomal miR-4669 on the suppression of M1 macrophage activity to generate an immunosuppressive tumor microenvironment." (PMID 37175615, 2023). "Tumor can product multiple inflammatory factors, such as IL1, TNFα and VEGF, which can induce endothelial cell activation, promote leukocyte recruitment and platelet adhesion, and generate FVIII and TF that accelerate thrombosis." (PMID 37386391, 2023). "N1 subtype secretes CCL3, CCL9, CXCL10, TNF-α, IL12, Cathepsin G, and neutrophil elastase (NE) to recruit, activate and induce proliferation of T-cells to implement anti-tumor influence and improve adaptive immune responses." (PMID 37376417, 2023). "In contrast, SCCNVs can deliver tumor antigens and proinflammatory cytokines (IFN-γ and TNF-α) simultaneously to DCs, leading to a higher efficiency of DC activation." (PMID 36854774, 2023). "FAP+ CAFs can protect tumor cells from tumor necrosis factor and interferon-mediated T-cell necrosis and can express CXC motif chemokine ligands, inhibiting T-cells from accessing tumor cells." (PMID 36793444, 2023). "The influx of functional T cells, i.e., T cells that produce anti-tumor cytokines, including IL-2, IFN-γ, and TNF-α, in the TME of the Lm-LLO-ISG15-vaccinated group was higher than that of the Control Lm-treated group." (PMID 36831577, 2023). "Serum level of tumor markers (AFU and TNF-α) of rats given T-2 toxin (0.1 mg/kg) after 2 months and treated with curcumin and taurine." (PMID 37214337, 2023). "Hypoxia-induced GAS5 promotes the anti-tumor effect of NK cells by sponging miR-18a in gastric carcinoma, increasing the secretion of IFN-γ, TNF-α, and targeting miR-544, upregulating the RUNX family transcription factor 3 in liver carcinoma." (PMID 36831498, 2023). "This analysis revealed that while in the heart of PyMT-bearing mice, INFγ and TNFα are at low levels; IL-13 and CCL2 are elevated in the PyMT tumor." (PMID 37508517, 2023). "Arnt−/− mice had more CD11b+Gr1+ neutrophil infiltration, fewer proinflammatory factor TNFα production, more anti-inflammatory factor IL-10 production and CXCR2 expression in neutrophils in tumor and draining lymph node (dLN) compared with WT control." (PMID 36859266, 2023).
tumor (continued). "Tumor-infiltrating pDCs are reported to produce immunosuppressive and carcinogenic effects; however, due to their ability to secrete INF-I and TNF-α, pDCs are potential therapeutic targets for combating cancer." (PMID 37513975, 2023). "When stimulated with tumor necrosis factor (TNF)α, human BM MSCs express TNF-related apoptosis-inducing ligand (TRAIL), induce apoptosis, and inhibit in vivo tumor formation in triple-negative BC cells." (PMID 37046676, 2023). "In tumor-bearing mice, PDT induced tumor growth inhibition in two different models and increased the serum levels of IFN-y, IL-6, and TNF-a after treatment." (PMID 36839652, 2023). "Our results showed that IL-6, IL-17, TNF-α, TLR-2 and TLR-4 genes were overexpressed in tumor tissues compared to adjacent normal tissues." (PMID 38075864, 2023). "Experiments of the hepatocellular carcinoma H22-bearing mice have showed that by raising the spleen and thymus indexes as well as increasing the cytokines like IL-2, IL-6, and TNF-α in serum, APS can affect immune-regulating features in tumor." (PMID 37741920, 2023). "M1-like macrophages inhibit tumor growth and facilitate cancer therapy via secreting chemokines, such as interleukin 6 (IL6) and tumor necrosis factor α (TNFα), whereas M2-like macrophages promote tumor growth." (PMID 37849457, 2023). "Primarily, the impact of transmembrane TNF derived from PMN-MDSCs on immune cells, beyond tumor-infiltrating CD8+ T cells, remains nebulous." (PMID 37455286, 2023). "Inflammatory mediators such as TNF-α, IL-1β, IL-6, and IFN-γ promote an increase in blood supply to the tumor." (PMID 37894468, 2023). "Metastasis cancer-1 and -2 subsets also shared common activated immune-related pathways (e.g., TGF-β, IL-6/JAK-STAT3, and TNF-α/NF-κB) that are closely related to EMT occurrence, tumor invasion, and metastasis." (PMID 37853464, 2023). "Tumor necrosis factor-alpha (TNF-α) and IFN-γ production are promoted when SLAMF4+ NK cells were co-cultured with tumor-infiltrating SLAMF2+/CD68+ monocytes/macrophages from patients with HCC." (PMID 37251372, 2023). "PAR1CAR-T cells secrete proinflammatory cytokines and chemokines, including TNF-α, IFN-γ, IL-1α, IL-4, IL-6, IL-17A, and GRO, upon encountering PAR1 antigens that exhibit potent cytolytic capacities against PAR1-expressing tumor cells." (PMID 37667257, 2023). "Intraperitoneal AgNPs treatment beginning on the day of tumor inoculation enhanced mice survival, reduced the proliferation of ascitic EAC cells, and suppressed the activity of HIF1α, TNF-α and VEGFa genes." (PMID 37111584, 2023). "Elevated expression of T cell activation markers CD25 and CD137, and the production of pro-inflammatory Th1 cytokines IL-2, TNF-α, and IFN-γ, at the tumor site were also consistent with heightened T cell activation when administered after carboplatin." (PMID 37660083, 2023). "Analysis of intratumoral lymphocytes in sgSlc38a2-transduced MC38 tumours revealed a higher frequency and number of intratumoral CD8+ T cells, including those expressing IFNγ, TNF or granzyme B, indicative of enhanced effector phenotypes." (PMID 37407815, 2023). "The H1-pAIM2/pCAIX vaccine activated CAIX-specific CD8+ T cell proliferation and a CTL response, stimulated multifunctional CD8+ T cells to produce TNF-α, IL-2, and IFN-γ, and significantly inhibited tumor growth." (PMID 36839868, 2023). "The expression of ARL4C exhibited a significant and positive correlation with immune-related pathways such as TNF-α/NF-κB, INF-γ, INF-α, IL-6/JAK/STAT3, and hypoxia signaling pathways, thereby establishing a connection between ARL4C and tumor immunity." (PMID 38178862, 2023). "Pro-inflammatory cytokines, such as IL-1α, IL-1β, IL-6, and TNF, showed higher amounts in the saliva of patients with OSCC, indicating the involvement of the inflammatory environment in tumor progression." (PMID 37686462, 2023).